OPCML-IT2 (OPCML intronic transcript 2)
Gene: Long non-coding RNA gene on chromosome 11 (132,859,245 to 132,860,077, reverse strand). Ensembl gene ENSG00000255371.
Diseases named in the same sentence as OPCML-IT2 in open-access papers:
OPCML-IT2 is named in the same sentence as 2 diseases in open-access papers, as found by Europe PMC text mining. Sharing a sentence is not in itself a finding about the gene and the disease. The quoted sentences say what the papers report.
cancer (1 paper, 2023). A tumor composed of atypical neoplastic, often pleomorphic cells that invade other tissues. "Some are known to be tumor suppressor genes (OPCML-IT2), to be related to resistance to cancer therapies (RAC1P3), or to be involved in several cancer processes such as genome stability (XRCC6P2), tumor growth and metastasis (MIR602) and regulation of gene transcription (NME2P2)." (PMID 36647008, 2023).
OPCML-IT2 also shares sentences with these, for which no sentence is quoted: tumor (1 paper).